GHRH (growth hormone releasing hormone)
Diseases named in the same sentence as GHRH in open-access papers (continued):
Sharing a sentence is not in itself a finding about the gene and the disease.
prostate carcinoma (18 papers, 1997 to 2025). A carcinoma that arises from epithelial cells of the prostate gland. "Other studies also show similar results with GHRH antagonist treatment in prostate cancer cells, associating reduced MMP2 and 9 activity with reduced tumour cell motility and invasiveness." (PMID 39456984, 2024). "GHRH antagonists caused a significant decrease in the expression levels of PCNA in prostate cancer cells and the observed tumor growth inhibition was associated with such a decrease on protein levels." (PMID 27448980, 2016). "Antagonists of GHRH have experimental therapeutic value, but as single agents are not likely to improve clinical outcomes, especially in advanced prostate cancer resistant to androgen deprivation therapy." (PMID 40427140, 2025). "Our objective is to identify anti-cancer drugs that, in combination with MIA-602 or -690 GHRH antagonists, increase cell death in all types of prostate cancer." (PMID 40427140, 2025). "Other studies have shown a similar effect on the cell cycle in prostate cancer after treatment with GHRH antagonists." (PMID 39456984, 2024). "In LNCaP prostate cancer cells GHRH antagonists exerted antioxidative properties, and in A549 lung cancer cells JV-1–36 suppressed hydrogen-peroxide induced ROS." (PMID 38957466, 2024). "mRNAs for GHRH or GHRH peptide were also found in surgical specimens of human endometrial, ovarian, breast and prostate cancers." (PMID 35566020, 2022). "Previous studies demonstrated that GHRH antagonist JMR-132 inhibits the growth of human prostate cancer xenografted into nude mice through the inactivation of ERK." (PMID 36232554, 2022). "GHRH-induced cAMP responses were subsequently measured in three prostate cancer cell lines expressing different levels of GHRHR and SV1." (PMID 34599099, 2021). "GHRH antagonists have been widely used to inhibit angiogenesis and proliferation of tumor cells in prostate cancer, endometrial cancer, non-small cell lung cancer, and ovarian cancer." (PMID 27774107, 2016). "Present results confirm and extend the role of GHRH antagonists as anti-proliferative and pro-apoptotic molecules in prostate cancer." (PMID 27448980, 2016). "Various in vitro and in vivo studies demonstrated that several GHRH antagonists suppress the growth and enhance apoptotic processes in prostate cancer and other experimental cancers." (PMID 27448980, 2016). "Other laboratories have also clearly shown the converse that GHRH antagonists powerfully inhibit angiogenesis and growth of lung cancer cells, prostate cancer cells, glioblastomas cells, and breast cancer cells." (PMID 27774107, 2016). "In the current study, we investigated the effect of GHRH antagonists on proliferation and apoptosis in human prostate non-tumor and tumor cells and an experimental model of advanced prostate cancer." (PMID 27448980, 2016). "It was further demonstrated that the GHRH antagonist JMR-132 inhibited prostate cancer cell growth by suppressing Akt and ERK pathways." (PMID 27774107, 2016). "These breast, lung and prostate cancer cell lines were also exposed in vitro to two concentrations of GHRH antagonists MZ-4-71, MZ-5-156 and JMR-132." (PMID 18506184, 2008). "Interestingly, the GHRH antagonist MZ-5-516 in prostate cancer cells, as well as MIA-602, MIA-606 and MIA-690 in non-small cell lung cancer cells, reduced VEGF secretion and attenuated the mRNA expression and activity of MMP2 and MMP9." (PMID 36232554, 2022). "The effect observed of GHRH antagonists observed on cell cycle correlates with the findings from cell proliferation assays as well as with the tumor reduction observed in advanced prostate cancer." (PMID 27448980, 2016). "Interestingly, GHRH stimulated and GHRH antagonist inhibited the expression of the major antioxidant enzymes in the LNCaP human prostate cancer line." (PMID 27777568, 2016).
prostate carcinoma (continued). "Tumour-inhibitory effects of a new antagonist of growth hormone-releasing hormone (GH-RH), MZ-4-71, were evaluated in nude mice bearing androgen-independent human prostate cancer cell lines DU-145 and PC-3 and in Copenhagen rats implanted with Dunning R-3327 AT-1 prostatic adenocarcinoma." (PMID 9184172, 1997). "GHRH antagonists have been implicated in the in vitro inhibition of a variety of cancer cell lines including but not limited to APL, AML, estrogen independent breast cancer, clear cell ovarian cancer, glioblastoma, gastric cancer, prostate cancer, and endometrial adenocarcinoma." (PMID 38588464, 2024). "Several receptors for GHRH have been described, both the pituitary-type receptor (pGHRH-R) and four variants generated by alternative splicing (SV1–SV4), which are expressed physiologically in various human tissues, and also in several types of cancer, including breast and prostate cancer." (PMID 39456984, 2024). "Consequently, GHRH antagonists could be considered good candidates in the design of new therapies in advanced prostate cancer." (PMID 27448980, 2016). "GHRH antagonists showed the greatest effects on both viability and proliferation in PC3 cells, which represent a highly aggressive stage in prostate carcinomas." (PMID 27448980, 2016). "In previous studies, we reported that the GHRH antagonists, JMR-132 and JV-1-38, significantly reduce tumor proliferation in mice xenografted with PC3 prostate cancer cells." (PMID 27448980, 2016). "It has been also shown that the GHRH antagonist JMR-132 had antiproliferative effects in lung, breast and prostate cancers, but the effect of JMR-132 on ovarian cancer cell lines was not reported." (PMID 20509930, 2010). "In the present study, we demonstrated by western blots the presence of the SV1 of GHRH receptor and the production of GHRH in MDA-MB-468, MDA-MB-435S and T47D human breast cancer cell lines, LNCaP prostate cancer cell line as well as in NCI H838 non-small cell lung carcinoma." (PMID 18506184, 2008). "However, MIA-602/690 GHRH antagonists alone are not likely to be effective against advanced prostate cancer." (PMID 40427140, 2025). "Knocking down of GHRH gene expression suppressed the proliferation of T47D, MDA-MB-435S, MDA-MB-468 breast cancers, LNCaP prostate cancer and NCI H838 non-SCLC." (PMID 38957466, 2024). "The knocking down of the GHRH gene expression suppressed the proliferation of T47D, MDA-MB-435S, MDA-MB-468 breast cancer, LNCaP prostate cancer and NCI H838 non-SCLC cell lines in vitro." (PMID 18506184, 2008). "Prostate cancer cell line LNCaP and non-SCLC cell line NCI H838 showed decreases in proliferation rates of 51.8 and 48.4% respectively after the inhibition of the GHRH gene expression." (PMID 18506184, 2008).
Hypoglycemia (13 papers, 2008 to 2026). A decreased concentration of glucose in the blood. "We modeled hypoglycemia insensitivity with repeated glucose deprivation in vivo and demonstrated blunted GHRH neuron activation associated with remodeling of excitatory and inhibitory inputs and microglial activation." (PMID 33148883, 2020). "Hypoglycemia has previously been shown to stimulate the secretion of GH via GHRH (growth hormone releasing hormone)." (PMID 40585323, 2025). "A 30-year-old man with MEN1, who was also diagnosed with nesidioblastosis and hypoglycemia, had an additional growth hormone-releasing hormone (GHRH) producing tumor, hyperparathyroidism, hyperprolactinemia, and multiple endocrine pancreatic tumors." (PMID 37371827, 2023). "GHRH neuron activity is decreased by both repeated 2DG and insulin-induced hypoglycemia, suggesting cells other than GHRH neurons likely maintain feeding with repeated insulin hypoglycemia." (PMID 33148883, 2020). "Further work examining the feeding and hormonal responses to GHRH neuron modulation is needed to determine their roles in hypoglycemia-induced feeding and pancreatic hormone release." (PMID 33148883, 2020). "In clinical studies, insulin-induced hypoglycemia increases GH even in individuals with GHRH insensitivity." (PMID 33148883, 2020). "GHRH neurons in the arcuate nucleus are activated by glucose deprivation; however, repeated hypoglycemia blunts activation, remodels inputs, and disrupts mitochondrial fusion." (PMID 33148883, 2020). "Insulin receptors are expressed on SST neurons, and insulin-induced hypoglycemia in combination with GHRH treatment has a greater effect on plasma GH than either alone." (PMID 33148883, 2020). "Repeated 2DG increased SST+ terminals on GHRH neurons, but SST+ terminals on GHRH neurons were unchanged with repeated insulin hypoglycemia." (PMID 33148883, 2020). "Our data suggest repeated hypoglycemia disrupts multiple points in the glucose-sensing network: glucose sensing in GHRH neurons as well as their inputs." (PMID 33148883, 2020). "Further studies are needed to assess the role of UCP2 or other pathways in mitochondrial remodeling with hypoglycemia in GHRH and other GI neurons." (PMID 33148883, 2020). "Transcriptional profiling of hypothalamic GCK cells in a model revealed a population of hypoglycemia-activated growth hormone releasing hormone cells, suggesting a role for brain GCK in generating growth hormone responses to hypoglycemia." (PMID 30146176, 2018). "GHRH release from N38 cells was increased by 40%–50% with hypoglycemia (1 time and 3 times; 1x and 3x), but this increase was blunted by repeated hypoglycemia (5 times; 5x)." (PMID 33148883, 2020). "In our studies, GHRH neuron activation is blunted by repeated 2DG or insulin treatment, suggesting that decreased GHRH activity may contribute to impaired CRR with repeated hypoglycemia." (PMID 33148883, 2020). "We also found that GHRH neurons are synaptically connected to the pancreas, so hypoglycemia-activated GHRH neurons could directly influence pancreatic endocrine function." (PMID 33148883, 2020). "GHRH activation was greater with 2DG than with insulin hypoglycemia." (PMID 33148883, 2020). "In addition, acute hypoglycemia increased the density of putative glucose sensor Gck in GHRH neurons by three-fold and doubled Ghrh mRNA probe density compared with vehicle treatment, and this increase was absent with repeated glucose deprivation." (PMID 33148883, 2020). "Similarly, both repeated 2DG and repeated insulin-induced hypoglycemia significantly reduced GHRH dendritic spine density." (PMID 33148883, 2020). "Because there are differences in the physiological responses to repeated glucose deprivation with 2DG versus repeated insulin-induced hypoglycemia, we assessed GHRH neuron activation, dendritic spine number, inhibitory inputs, and plasma GH in response to repeated insulin-induced hypoglycemia." (PMID 33148883, 2020).
Hypoglycemia (continued). "However, there was no significant change in SST-containing terminals contacting GHRH neurons with repeated insulin-induced hypoglycemia." (PMID 33148883, 2020). "Glucose also exerts a hormonal-like action on neurons; electrophysiological recordings demonstrated, for example, that hypoglycemia activates growth hormone-releasing hormone (GHRH) neurons, suggesting a mechanistic link between low blood glucose levels and growth hormone release." (PMID 25698989, 2015). "In very young children, the GHRH-arginine test may not conclusively differentiate GH deficiency from normal and the insulin tolerance test may result in hypoglycemia due to high sensitivity to insulin." (PMID 29375479, 2017). "The most commonly used secretagogues include insulin-induced hypoglycemia [insulin tolerance test (ITT)], arginine [arginine stimulation test (AST)], clonidine, glucagon, levodopa, and growth hormone releasing hormone (GHRH)." (PMID 33362716, 2020). "Secretion of GH depends on GHRH, somatostatin (GH-inhibiting hormone, GHIH), and ghrelin, but several other factors are undoubtedly involved in the regulation of GH secretion (e.g., thyroid hormones, hypoglycemia)." (PMID 41155234, 2025). "GHRH mRNA was not significantly increased by a single episode of hypoglycemia, but repeated hypoglycemia (5x) significantly reduced GHRH expression." (PMID 33148883, 2020). "Given the complexity of the GHRH-SST-GH system in vivo, we sought to recapitulate blunted hypoglycemia sensing with repeated glucose deprivation using an in vitro system, independent of alterations in excitatory/inhibitory inputs or feedback from circulating hormones." (PMID 33148883, 2020). "Both acute insulin-induced hypoglycemia and glucose deprivation by 2DG activated GHRH neurons, and this effect was absent with repeated 2DG-induced and repeated insulin-induced hypoglycemia." (PMID 33148883, 2020). "Our previous research has demonstrated that mice lacking functional growth hormone‐releasing hormone (GHRH) exhibit distinct physiological characteristics, including an extended lifespan, a preference for lipid utilization during rest, mild hypoglycemia, and heightened insulin sensitivity." (PMID 37667562, 2023). "Our data demonstrate that GHRH neurons are GABAergic, non-AGRP, non-POMC ARC neurons and activated by hypoglycemia and so could contribute to feeding response." (PMID 33148883, 2020). "Patients with MEN1 often present with multiple pNETs, which may exhibit multihormonal secretion and frequently cosecrete GHRH and insulin in MEN1, while hypoglycemia may not be manifested possibly due to GH and insulin's counteractive effects on glucose metabolism." (PMID 42007244, 2026).
adenoma (12 papers, 2008 to 2026). A neoplasm arising from the epithelium. "On the other hand, in a hyperplastic context, it has been suggested that endogenous SST does play a role in suppressing the expansion of the somatotroph population and slowing adenoma formation in response to ectopic GHRH excess." (PMID 37576961, 2023). "On the other hand, GHRH reduces the K+ current in human adenoma cells as well as in GH4C1 cells; the synthetic analogue of ghrelin, GHRP-6, diminishes both the transient and the delayed rectifier currents in rat somatotropes." (PMID 23533398, 2013). "In this case, the main actor would be growth-hormone-releasing hormone (GHRH), which can cause not only hyperplasia of somatotrope cells but also, as demonstrated in some animal models, actual adenomas." (PMID 18578866, 2008). "However, endogenous SST primarily controls GHRH-induced adenoma formation via modulation of apoptotic and/or cellular senescence pathways in a hyperplastic context." (PMID 37576961, 2023). "The GHRH-arginine test may be the test of choice when a primary pituitary defect is presumed (i.e., pituitary surgery or adenoma), where GHRH is available." (PMID 35465075, 2022). "Of the three “silent” adenomas, tumor 1, a silent GH adenoma, responded predominantly to GHRH and to a lesser extent to GnRH and TRH, whereas tumor 13, a silent ACTH adenoma, responded similarly to GHRH, CRH, TRH, and TRH/DA." (PMID 38612778, 2024). "The other two previously reported adenomas were made of cells storing no hormone or mostly ACTH and showing responses to CRH and TRH and to a lesser extent to GHRH suggesting a corticotrope ontogeny." (PMID 26106585, 2015).
lung carcinoma (12 papers, 2008 to 2025). "Overall, these results suggest that GHRH antagonists enhance the cytotoxic effects of IR in lung cancer cells." (PMID 40244089, 2025). "The expression of GHRH has been demonstrated in prostatic, endometrial, ovarian, breast, gastroenteropatic, and lung carcinomas, glioblastomas, malignant bone tumors, human adrenal carcinomas and colorectal cancers." (PMID 38957466, 2024). "Antagonists of growth hormone-releasing hormone (GHRH) display strong antitumor effects in many experimental cancers, including lung cancer and mesothelioma." (PMID 36232554, 2022). "GHRH peptide antagonists have been shown to trigger apoptotic cell death via inhibiting the GHRH signaling in the prostate, endometrial, colon, lung cancer in vitro and in vivo." (PMID 35061691, 2022). "GHRH is a neuropeptide that is known to be ectopically expressed in many cancer types such as the pancreas, prostate, ovarian and lung cancer." (PMID 35061691, 2022). "Elevated levels of serum growth hormone, growth hormone-releasing hormone, vascular endothelial growth factor and platelet-derived growth factor have been reported in certain patients with lung cancer and HPO." (PMID 24932292, 2014). "Studies of GHRH antagonists on prostate and lung cancers demonstrated their ability to modulate signaling pathways involved in cellular proliferation, survival, metastasis, and apoptosis." (PMID 22941871, 2012). "Studies of GHRH antagonists on prostate and lung cancers demonstrated the ability to modulate signaling pathways involved in cellular proliferation, survival, metastasis, and apoptosis." (PMID 22941871, 2012). "Since studies in diverse systems demonstrate GHRH-R in lung cells, and since GHRH-R antagonist modulates inflammation, fibrosis, and lung cancer, GHRH has certain biological importance in the lung and appears to participate in physiologic processes beyond lung injury and repair." (PMID 33096674, 2020). "GHRH was shown to cause MAPK activation in MDA-MB-231 breast cancer cells via phosphorylation of Ras and Raf, and the GHRH antagonists MZ-J-7-138 and JV-1-92 were shown to block this pathway and suppress lung carcinoma growth in a manner that correlated with Ras inhibition." (PMID 27774107, 2016). "Previous in vivo studies in lung cancer showed that decreased EGFR level might be involved in the antiproliferative effect of GHRH antagonists, but it hasn't been reported in ovarian cancer cell lines by JMR-132 treatment." (PMID 20509930, 2010). "GHRH antagonists were shown to inhibit the proliferation both in vivo and in vitro of various human cancers, including pancreatic, colorectal, prostatic, breast, renal, glioblastomas, osteosarcomas and Ewing sarcomas, lung carcinomas, lymphomas, as well as ovarian and endometrial cancer." (PMID 20509930, 2010). "GHRH can also activate: i) JAK2/STAT3, which contributes to oxidative phenomena, and ii) inducible nitric oxide synthase (iNOS) in A549 lung cancer cells." (PMID 38957466, 2024). "Along with endocrine effects on the GH/IGF-I axis, direct mechanisms likely include blockade of the autocrine/paracrine activity of GHRH and IGF-I/II in lung cancers." (PMID 33096674, 2020). "The importance of the results analyzed in this work led us to design an in vivo study in PC-3 tumours on the combined effect of the GHRH antagonist MIA-690 and the reversible EGFR inhibitor Gefitinib, a chemotherapeutic agent approved for clinical use in lung cancer." (PMID 39456984, 2024). "GHRH and its receptors (GHRH-Rs) have been identified in both normal lung and lung cancer tissues." (PMID 40244089, 2025).